ERBB2 (erb-b2 receptor tyrosine kinase 2)
Diseases named in the same sentence as ERBB2 in open-access papers (continued):
Sharing a sentence is not in itself a finding about the gene and the disease.
tumor (continued). "It is unclear which impact nuclear ErbB2 expression in HCC has on tumor behavior and whether nuclear localized ErbB2 could be therapeutically targeted by trastuzumab and other ErbB2-directing molecules." (PMID 32591879, 2021). "Additionally, Ginath et.al reported that ERBB2 (host gene of m7G_ID_268139) activates multiple downstream signaling pathways, and then promotes the proliferation, invasion, and metastasis of tumor cells." (PMID 33761868, 2021). "It promotes tumor progression and migration through interaction with ErbB2." (PMID 33630973, 2021). "Nuclear ErbB2 expression in tumor cells results in a poor prognosis and might mediate chemoresistance and radioresistance." (PMID 32591879, 2021). "In these tumours, ERBB2 showed, as expected, extremely strong membrane staining." (PMID 34003256, 2021). "Lapatinib, the inhibitor of ERBB2, cannot compromise ++Oxtr tumor growth." (PMID 34099636, 2021). "Notably, ERBB2 amplification causes the overexpression of tyrosine kinase receptor HER2, which triggers the downstream hyperactivation of PI3K/AKT and mitogen-activated protein kinase (MAPK) pathways and which results in tumor cells proliferation and survival." (PMID 34281208, 2021). "Patients with dominant C > A/T mutational patterns associated with aging processes might benefit from conventional chemotherapy (in combination with ERBB2 inhibition) since the tumor’s genome is more stable." (PMID 34503107, 2021). "Tumor histological grade also predicted cancer ERBB2 status in the FinProg series (P < 0.001)." (PMID 33597560, 2021). "During tumor growth, stable surface expression of ERBB2 was shown." (PMID 33809981, 2021). "Consistently with both approaches, ERBB2 amplification could be detected in tissue samples of primary tumor and liver metastasis, and in cfDNA before chemotherapeutic treatment, but not after chemotherapy." (PMID 34408162, 2021). "Also, as previously reported several patients had tumours with multiple putative oncogenic driver, including patients with ERBB2 amplified tumours that had co-amplification of other oncogenes." (PMID 34794033, 2021). "A previous study demonstrated that the inhibition of ERBB1 and ERBB2 could rapidly inhibit the motility and intravasation of tumor cells." (PMID 34857007, 2021). "ERBB2, CEBPA and TCF7L2 mutated tumors tend to have higher tumor mutation burden (TMB)." (PMID 34970478, 2021). "Indeed, p140Cap confers to ERBB2 transformed cells both limited in vivo tumor growth ability and impaired spontaneous lung metastasis formation." (PMID 34708040, 2021). "Eventually, it is known that B4GALNT1 is a relatively ideal target, but targeting GPC3 and ERBB2 might lead to severe “on-target, off-tumor toxicity” in some tissues." (PMID 34975912, 2021). "Although our sample size is limited, this effect seemed to be driven by the survival of patients with ERBB2-amplified tumours who all received trastuzumab-based therapy (as expected), but also by the overall survival of patients with other alterations who received matched therapy." (PMID 34794033, 2021). "The contradictory studies looking at ERBB2 expression and the correlation to outcomes in patient tumor tissue could reflect differences in results both in the composition and size of cohorts studied or by differing sources of antibodies used in the studies." (PMID 33918389, 2021). "The distribution of EGFR and ErbB2 expression in the xenograft tumor has been previously reported." (PMID 34832857, 2021).
tumor (continued). "Due to local and pulmonal tumor progression after 6 months and persistent ERBB2 positivity, the therapy was adjusted to trastuzumab emtansine (T-DM1) 3.6 mg/kg q3w; however, the patient remained locally progressive after three cycles of T-DM1 and additionally showed a new bone metastasis." (PMID 34367146, 2021). "Indeed, a significant reduction in tumor cell proliferation was observed with the inhibition of ErbB3–ErbB2 complex formation by monoclonal antibodies that targeted ErbB2." (PMID 33652578, 2021). "Here we uncovered a previously unknown role of p63 (specifically, TAp63) as a cell-autonomous tumor suppressor in PIMECs that curbs their intrinsic tumorigenic properties in parous ErbB2 females." (PMID 34023861, 2021). "It has been reported that ERBB2 promotes tumor progression especially in skin and breast cancers." (PMID 34446793, 2021). "Display of overexpressed ErbB2 at the cell surface following its biosynthesis in the endoplasmic reticulum is required for oncogenesis, but mechanisms that regulate how this process is optimized in tumor cells are poorly understood." (PMID 34439093, 2021). "CB2 expression was also found to be correlated with tumours that had a low response to conventional therapies and that were also positive for certain prognostic markers including oestrogen, progesterone receptors and the presence of ERBB2/HER-2 oncogene." (PMID 34259916, 2021). "Furthermore, human SRCIN1-flanking regions contain several genes involved in tumor initiation and progression, such as ERBB2 (17q12), BRCA1 (17q21), retinoic acid receptor-α (RARA; 17q21) and signal transducer and activator of transcription 3 (STAT3; 17q21)." (PMID 33079227, 2021). "The expression of ErbB2 on tumor cells in vivo was evaluated by IHC as well." (PMID 34561494, 2021). "Related to the predictive information of the H&E-ERBB2 score that we found to complement the ERBB2 gene amplification status, one could speculate that the CNN has learned auxiliary tumor features associated with efficacy of trastuzumab therapy and DDFS." (PMID 33597560, 2021). "The results revealed that a p140Cap positive status was associated with negative lymph node status, ER and progesterone receptor (PgR)-positive status, small tumor size, low grade, low Ki67 status, and correlates with a better prognosis in ERBB2-positive patients." (PMID 34708040, 2021). "Secondly, HER2 itself can trigger an anti-tumor immune response in tumors amplified by ERBB2." (PMID 35095993, 2021). "Tumours with high expression of both ERBB2 and ESR1 could be of special interest, since these seem to interact with each other under endocrine therapy, providing a resistance mechanism." (PMID 34073233, 2021). "Previous studies have shown that mutations in ERBB2 may increase HER3 phosphorylation, which can attenuate the anti-tumour effect of some PI3K inhibitors." (PMID 33933113, 2021). "All but one patient with ERBB2 amplification identified in this study had concomitant overexpression of HER2 by IHC and had received HER2-targeted therapy as standard of care (fluoropyrimidine and platinum combined with trastuzumab in all cases) prior to molecular tumour board meeting." (PMID 34794033, 2021). "This individual harbored an ERBB2 c.3250G > T; p.D1084Y variant, reported as a rare germline variant in Europeans and absent from tumor samples in the GDC database." (PMID 34209587, 2021). "The present study suggests that machine learning can be used to extract predictive information when applied to routine tumor tissue sections and may help in identifying patients with ERBB2-positive cancer who would benefit the most from adjuvant trastuzumab." (PMID 33597560, 2021). "ERBB3 knock‐down in ERBB2‐amplified mammary cancer cells blocked tumor formation." (PMID 36618440, 2021).
tumor (continued). "Here, we harnessed the dual-recognition potential of NKp30+CD8+ T cells, by arming these cells with TCRs or chimeric antigen receptors (CARs) targeting Epidermal Growth Factor Receptor 2 (ErbB2, or HER2), a tumor-associated target overexpressed in several malignancies." (PMID 35036073, 2021). "Indeed, in a pre-clinical model using cell line in vivo assays, it was demonstrated that EGFR promotes the survival of PC-circulating tumor cells, while ERBB2 supports cancer cell growth in bones by promoting the RANK signaling pathway." (PMID 33918389, 2021). "The BsAb binds to the recombinant ErbB2 receptor, as well as to lysates of ErbB2+ tumor cell lines." (PMID 34944558, 2021). "To investigate the potential of NK-92/5.28.z cells to lyse aRMS cells growing in 3D culture, we established RH30 and RH41 tumor spheroids and used them to compare the killing capacity of the ERBB2-CAR-NK-92 cells with that of parental NK-92 cells over a time period of 10 days." (PMID 33809981, 2021). "Supporting a role of pH during carcinogenesis, oral NaHCO3 therapy impairs primary tumor growth in the transgenic adenocarcinoma of the mouse prostate (TRAMP) model, and knockout of NBCn1 delays carcinogen- and ErbB2-induced breast cancer development and decelerates tumor growth." (PMID 32268614, 2020). "ERBB2 amplification has been identified as a resistance mechanism induced upon treatment with erlotinib or gefitinib and was observed in 12% of tumor samples obtained from patients at resistance to EGFR TKI therapy; however, its role in afatinib resistance is unclear." (PMID 32477948, 2020). "We report here a clinically relevant orthotopic mouse model of ERBB2+ BC that spontaneously metastasizes to brain and demonstrates that targeting the c-MET/ERBB1 axis with a combination of cabozantinib and neratinib decreases primary tumor growth and prevents brain metastasis in ERBB2+ BC." (PMID 33019652, 2020). "Taken together, these analyses revealed alterations that would have otherwise been masked in bulk analysis of the OCI-C5x population and indicate that the ERBB2 amplification is present at a low frequency in the original tumor and the OCI-C5x parental line derived from it in vitro." (PMID 33199705, 2020). "However, cytotoxicity triggered by interaction of their activating NK receptors with stress ligands expressed by tumor cells was retained by ERBB2-CAR-CIK cells." (PMID 33193388, 2020). "ERBB2 has been reported as an amplified oncogene in cancer and its protein overexpression has been associated with high grade and high-stage, NEEC histologies, the degree of tumor progression and the outcome and survival of the patients." (PMID 32560580, 2020). "Recent studies implicated HA-CD44 interaction in tumor cell resistance to chemotherapy, by inducing multi-drug resistance 1 gene (MDR1) expression, ABC drug transporters, ankyrin-induced drug fluxes, and tumor cell survival pathways like ErbB2 signaling and PI3K/AKT pathway." (PMID 32793493, 2020). "Human ERBB2 could be identified on tumor cells from spleens via IHC, whereas detection in intrahepatic cancer tissue (with more mitotic activity) was not possible due to autofluorescence of the liver tissue and bile." (PMID 33193388, 2020). "The 729 diagnostic tumor samples that were evaluated with the smMIP panel showed 788 (likely) pathogenic mutations, including mutations that give access to targeted treatment options (e.g. mutations in EGFR, BRAF, MET, ERBB2, KIT, PDGFRA)." (PMID 32264863, 2020).
tumor (continued). "Soluble factors, such as AREG, secreted by the non-tumorigenic and transient clonal populations that act in a “hit-and-run” fashion and are later dispensable, induce the ability of the ERBB2-amplified tumor cells to initiate solid peritoneal metastasis by promoting mesothelial clearance." (PMID 33199705, 2020). "In the randomized EMILIA trial, which compared T-DM1 and capecitabine-lapatinib (CL) for pretreated metastatic HER2+ BC patients, patients with tumor ERBB2 mRNA levels above median showed a greater benefit from the use of T-DM1 in terms of ORR and overall survival (OS)." (PMID 32674482, 2020). "In addition to genetic manipulation, novel bispecific antibodies simultaneously binding Vγ9 on γδ T cells and Her2/neu (ERBB2) expressed by tumour cells have been used to increase Vγ9Vδ2 T cell antitumour cytotoxicity." (PMID 32235722, 2020). "Preemptive ERBB2-CAR CIK cells and, to a lesser extent, WT CIK cells produced an effective antitumor response associated with the presence and prolonged persistence of immune cells at tumor sites." (PMID 33193388, 2020). "We hypothesized that deficient checkpoints and the increased proliferation of H/−;ErbB2 cells confer a positive selection for p53LOH during tumor progression." (PMID 33267874, 2020). "According to GSEA based on MDM2 expression, the ERBB2 and tumor angiogenesis pathways activated by MDM2 amplification may serve as important pathways inducing primary resistance to EGFR-TKIs." (PMID 32611363, 2020). "This patient had an amplification of the ERBB2 region present in both the tumor and EDO." (PMID 32884042, 2020). "Active immunization targeting ErbB2 might sustain tumor inhibition more effectively than passive immunotherapy based on the stimulation of a sustained memory immune response." (PMID 32423101, 2020). "Of these 40 patients, 14 patients (35.0%) had a tumor with an ERBB2 amplification." (PMID 31745978, 2020). "Several mechanisms have been identified as responsible for the inhibitory effect of anti-ErbB2/Neu antibodies in tumor cells expressing ErbB2/Neu: antibody-dependent cellular cytotoxicity (ADCC), complement-dependent cytotoxicity (CDC), and apoptosis induction or downregulation of receptor." (PMID 32423101, 2020). "ErbB receptor partial agonists have already been translated to clinical practice, as the FDA-approved anti-ErbB2 monoclonal antibody transtuzumab stimulates ErbB2 tyrosine phosphorylation and downregulation, resulting in reduced ErbB2-dependent tumor cell proliferation." (PMID 33378376, 2020). "Additionally, this study showed that Blimp1 expression was negatively regulated by mir-23b, suggesting a role as a tumor suppressor for this miRNA in p130Cas/ErbB2 cells." (PMID 32290321, 2020). "Indeed, mutations in ESR1, ERBB2 and NF1 were significantly enriched in ER+/HER2− tumours post hormone treatment compared to tumours from ER+/HER2− untreated patients." (PMID 32244556, 2020). "This correlates well with our in vivo mouse tumor data where ERBB2 positivity is observed." (PMID 30611309, 2019). "Moreover, the NF-kB-activating protein IKK-α supports ErbB2-induced tumor initiating cells expansion promoting nuclear export of p27, a negative regulator of the G1/S phase transition." (PMID 30621730, 2019). "Among the tumor-related genes, the top amplified genes included ERBB2 (17q21), MYC (8q24), GNAS (20q13), EGFR (7p11), ZNF217 (20q13), CCNE1(19q12), NCOA3 (20q13), and CDK6 (7q21), and the most frequently deleted genes were CDKN2A (9p21), CDKN2B (9p21), KIT (4q12), SMAD4 (18q21), and FGFR1 (8p12)." (PMID 31541076, 2019). "The relatively high ErbB1 and ErbB2 mRNA expression in IEC-6 jejunal cells compared to Walker 256 tumour cells may partially explain differential sensitivity to lapatinib." (PMID 31905843, 2019).
tumor (continued). "In this study, four such patients had a much shorter time to distant metastatic relapse as compared to both patients with no detectable DTCs and importantly, patients with ERBB2-positive DTCs who were treated with Trastuzumab because their primary tumor was also ERBB2 positive." (PMID 31432366, 2019). "The noticeable anti-tumor effect at molecular and cellular level of denosumab, when combined with anti-ERBB2 agents in ERBB2-positive BC cells, raises the possibility for therapeutic strategies with existing drugs, at least in a specific BC subgroup of RANK-expressing ERBB2-positive patients." (PMID 31796128, 2019). "However, these dual CAR-T cells only eliminated ERBB2+ tumor cells, and produced modest IL-2 in response to co-stimulation with a second antigen when compared to a control CAR-T cells expressing CD28 and CD3ζ endodomain." (PMID 31429760, 2019). "In addition, the same study showed anti-tumor cytotoxicity of ErbB2-CAR CIK against three-dimensional tumor spheroid models." (PMID 31212634, 2019). "We also compared human tumor-derived cells with high (HER3+ MDA-MB-435 cells) or low/undetectable (HER3− MDA-MB-231 cells) cell surface HER3 expression but with comparable levels of ErbB2 in the cell cytoplasm." (PMID 31617560, 2019). "Interestingly, in ERBB2 transformed cells, p140Cap exerts a suppressive function on migratory and invasive features, with a negative regulatory impact on the molecular pathways that ERBB2 exploits for tumor progression, such as the Tiam1/Rac GTPase axis." (PMID 31681758, 2019). "Indeed, a point-mutated sema3E resistant to cleavage by furin-like pro-protein convertases inhibits angiogenesis and tumor progression but is unable to activate ErbB2 and is unable to promote tumor metastasis." (PMID 30696103, 2019). "ERBB2 amplification was identified only in the tumour with HER2 3+ expression." (PMID 30837681, 2019). "Through its epidermal growth factor (EGF) domains, MUC4 may act as an intramembrane ligand for receptor tyrosine kinase ErbB2 and execute antiapoptotic function and by that promote tumor progression." (PMID 31091244, 2019). "CAR-T cells with decreased affinity to ErbB2 could discriminate tumor cells with high and low level ErbB2 from normal cells with physiologic level ErbB2." (PMID 31429760, 2019). "However, when overexpression of c-Myc in this animal model was combined with gain-of-function of another oncogene, Her2 (other name Erbb2: erb-b2 receptor tyrosine kinase 2), tumor penetrance reached 100%." (PMID 30836996, 2019). "Of 42 HER2+ tumor samples (based on ddPCR), lcWGS detected ERBB2 amplification in 40 samples." (PMID 31827209, 2019). "To select OECCL suitable for the production of cell lysates as the source of multiple tumor antigens, we first determined the expression levels of well-established OEC-associated antigens (CA-125, MUC1, ErbB-2, CEA, and survivin) in the CAOV3, SKOV-3, Hey, and A2780 cell lines by flow cytometry." (PMID 31886313, 2019). "However, other events distinguish the two tumor types, with primary MOC carrying ERBB2 amplifications and RNF43 mutations, whereas pancreatic tumors show frequent SMAD4 alterations." (PMID 31477716, 2019). "Mechanistically, GPAA1 enhanced the levels of metastasis-associated GPI-anchored proteins to increase tumour metastasis and intensified lipid raft formation, which consequently promoted the interaction between EGFR and ERBB2 as well as downstream pro-proliferative signalling." (PMID 31118109, 2019). "For example, the organoid culture OT330 and its donor tumor harbored an ERBB2 amplification." (PMID 30925167, 2019).